LEP (leptin)
Diseases named in the same sentence as LEP in open-access papers (continued):
Sharing a sentence is not in itself a finding about the gene and the disease.
malnutrition (continued). "It remains to be evaluated whether the malnutrition prior to or even the weight loss during the course of active VL potentiates the decrease of serum levels of leptin." (PMID 30913261, 2019). "Similar in structure to interleukin 2, an important T-cell growth factor, leptin modifies proinflammatory immune responses and may provide a key link between nutritional deficiency and immune dysfunction." (PMID 18489748, 2008). "Consequently, it can be hypothesised that subthreshold restrictive behaviours could lead to a state of latent malnutrition with associated alterations in leptin levels." (PMID 39643920, 2025). "Due to the crucial role of macrophages in the clearance of amastigotes, we hypothesized that weight loss in VL, either due to previous malnutrition or even during the course of the disease could lead to reduction of the leptin levels, which in turn could impair microbicidal functions." (PMID 30913261, 2019). "Malnutrition, especially a low BMI (<18.5 kg/m2), is a well-documented trigger for hypothalamic suppression, with leptin levels playing a central role." (PMID 41209456, 2025). "Chronic energy deficiency, malnutrition, or conditions such as anorexia suppress BDNF and leptin signaling, resulting in decreased GnRH release and delayed or absent pubertal progression." (PMID 41614834, 2025). "The ROC analysis identified albumin, leptin, myostatin, and adiponectin as biomarkers of malnutrition diagnosed using the 7-Point SGA." (PMID 39125361, 2024). "It must be noted that the leptin-centered research front relied on an adult rodent starvation model of questionable relevance to acute prepubescent malnutrition." (PMID 38068780, 2023). "One study tested the combination of the effects of malnutrition during the gestation period with the effects of leptin treatment on the offspring." (PMID 37507901, 2023). "Leptin, an adipocytokine, regulates the balance between food intake and energy expenditure, and a low level of leptin has been considered a biomarker of malnutrition and/or starvation." (PMID 36985226, 2023). "Some studies proved that leptin participates in the development of malnutrition in CKD, but further investigations are needed to comprehend the exact mechanisms of weight loss in this group of patients." (PMID 36675692, 2022). "Under the condition of malnutrition, the fat reserves decline therewith leptin level secreted by adipocytes decreases." (PMID 35267960, 2022). "Leptin secretion is proportional to the adipocyte mass and to malnutrition results in hypoleptinemia." (PMID 35011102, 2022). "In CKD patients on dialysis treatment, leptin correlated inversely with malnutrition–inflammation score, while adiponectin presented a weak positive correlation, suggesting an association between the increase in adiponectin with a worse nutritional status." (PMID 36289903, 2022). "For low leptin level under malnutrition, malnutrition is a common complication in IBD patients with a prevalence between 6.1% and 69.7%, which depends on different screening standards." (PMID 35267960, 2022). "In both sexes, the median leptin level increased significantly with the increasing BMI class, and decreased significantly with the increasing malnutrition class (as assessed by the MNA score)." (PMID 35011102, 2022). "Physiological changes affecting appetite are frequent and include appetite hormone (ghrelin, leptin, PYY, and GLP-1) effects and the subjective loss of appetite, resulting in nutritional deficiencies." (PMID 35162760, 2022). "For example, problems with the secretion of lymphocytes, albumin, and cytokines during periods of malnutrition and secretion of leptin in the context of sepsis." (PMID 34382503, 2021). "Similarly, in patients with malnutrition, in whom leptin deficiency is present, the same changes occur and these are reversible to the administration of exogenous leptin, emphasizing the possible therapeutic role of leptin analogues in the control of infectious diseases." (PMID 33907162, 2021).
malnutrition (continued). "Malnutrition reduces circulating leptin levels and suppresses sexual function; however, the condition can be rescued by leptin administration." (PMID 34944013, 2021). "Thymus growth and function is regulated by several hormones including Leptin, Prolactin and Growth hormone, mediated by insulin-like growth factor 1, all of which are low in malnutrition." (PMID 33397296, 2021). "WAT contains large lipid droplets and releases adipokines (FFAs, TNF-α, IL-6, IL-10, resistin, leptin, and adiponectin) to maintain metabolic homeostasis and stores TG for future energy production during periods of malnutrition." (PMID 33947969, 2021). "On the other hand, the elevated blood levels of leptin during malnutrition was an intriguing observation, since leptin production is usually proportional to body fat mass while adiponectin levels are usually inversely correlated with adiposity." (PMID 32525953, 2020). "Intriguingly, the systemic leptin levels are reduced in malnutrition and in starvation, suggesting that leptin bridges a link between the nutritional status and immune system of individuals." (PMID 32824322, 2020). "Decreased leptin serum levels during malnutrition would compromise its immunoregulatory and anti-apoptotic functions in the thymus, where it acts through the leptin receptors present on thymocytes and reticulo-epithelial cells." (PMID 32823553, 2020). "The adipocyte-secreted hormone leptin has been indicated as a possible mediator of malnutrition-induced thymic atrophy in mammals." (PMID 32823553, 2020). "Low serum leptin concentration serves as a biomarker for malnutrition and is related to reduced generation of proinflammatory cytokines and increased risk for infectious disease." (PMID 33304252, 2020). "This is compatible with previous studies showing that leptin is a biological marker for evaluating malnutrition." (PMID 31703113, 2019). "Despite identification of leptin as a hallmark biomarker in malnutrition, a previous study also verified a drastic fall in the serum leptin levels in L. donovani infected mice fed with a normal diet, confirming that the circulating leptin levels might be downregulated during Leishmania infection." (PMID 30913261, 2019). "The pro-inflammatory immune response, mediated by the low leptin levels, is also impaired during malnutrition." (PMID 31394828, 2019). "Serum leptin concentration decreases as malnutrition becomes more pronounced and thus serves as a biomarker of poor nutritional status in chronic cirrhosis due to viral hepatitis and candidiasis due to Candida albicans." (PMID 30534129, 2018). "Normal nutrition group had significantly higher albumin and leptin levels as well as GNRI than the malnutrition group." (PMID 30089153, 2018). "Malnutrition is characterized by the lower serum leptin level which in turn adversely alters the development of innate and adaptive immune responses during VL in both mice and children living in endemic areas." (PMID 30534129, 2018). "We review herein, the recent advances on the role of leptin in malnutrition in pathogenesis of infectious diseases with a particular emphasis on parasitic diseases such as Leishmaniasis, Trypanosomiasis, Amoebiasis, and Malaria." (PMID 30534129, 2018). "Present review provides a rationale for future studies to explore role of leptin as therapeutics to host immune dysfunction in infectious diseases during malnutrition." (PMID 30534129, 2018). "Understanding how leptin is altered in malnutrition and infection will lead to better insight of and treatment for diseases where nutritional status determines clinical outcome." (PMID 30534129, 2018). "A recent study on Bangladesh population suffering from amoebic liver abscess caused by E. histolytica, provides a significant correlation between disease severity and low serum leptin levels to malnutrition." (PMID 29868503, 2018). "The aim of the present study was to unravel the prophylactic role of leptin in malnutrition-coupled VL mice." (PMID 29116252, 2017).
malnutrition (continued). "It is possible that, in these cases, low leptin levels simply reflect malnutrition status, which is also related to frailty." (PMID 28400989, 2017). "In conclusion, we provide evidence for that exogenous leptin can restored the suppression of anergic T cells and favour GM-CSF expression in monocytes in malnutrition coupled L. donovani infection in BALB/c mice." (PMID 29116252, 2017). "Patients with chronic liver diseases are usually thin as a result of hypermetabolism and malnutrition expressed by reduced levels of leptin and impairment of other adyponectins such as visfatin." (PMID 27941973, 2016). "Third, logistic regression analysis revealed that besides log-transformed leptin, INR independently associated with malnutrition in hospitalized cirrhotic patients." (PMID 27583675, 2016). "Low serum leptin and elevated INR are associated with malnutrition in hospitalized patients with end-stage liver disease." (PMID 27583675, 2016). "Similar to RA, the importance of leptin has been demonstrated in cardiovascular disease, malnutrition, and sepsis, where low serum levels of leptin are unfavourable for survival." (PMID 27041823, 2016). "In conclusion, low serum leptin levels and elevated INR were associated with malnutrition in hospitalized patients with decompensated cirrhosis." (PMID 27583675, 2016). "In multivariable analysis, log-transformed leptin and INR were independently associated with malnutrition, and this relationship persisted after adjusting for race, gender, and age." (PMID 27583675, 2016). "In yet another study, decreased levels of leptin were observed in mice with prolonged fasting and malnutrition." (PMID 26241963, 2015). "The first showed lower BMI z score and lower weight forage (p=0.05 and p=0.01, respectively), and lowerlevels of leptin, suggesting malnutrition." (PMID 25511006, 2014). "In this study, low leptin levels were found to be the single most important biomarker to predict mortality during inpatient treatment of malnutrition." (PMID 25157251, 2014). "We investigated the consequences of mild maternal malnutrition in rat dams, in terms of thymocyte responses and the putative role of leptin." (PMID 23675529, 2013). "Malnutrition defined as serum leptin concentration <4 ng/mL in males and <6.5 ng/mL in females was observed in 33.8% of patients (equal in both sexes)." (PMID 22518129, 2012). "Leptin has been shown to prevent lymphoid atrophy, reconstitute lymphoid cellularity and to restore circulating lymphocyte populations during malnutrition." (PMID 21695035, 2011). "Among the mechanisms responsible for malnutrition, leptin was believed to influence nutritional markers in patients with ESRD." (PMID 21676262, 2011). "According to all the conditions mentioned, it can be concluded that serum leptin level cannot be considered as a marker for malnutrition in hemodialysis patients and more studies should be done with larger sample size that include healthy control group." (PMID 20142915, 2008). "This study was designed and performed to investigate the correlation between serum leptin level and malnutrition parameters in hemodialysis patients." (PMID 20142915, 2008). "Our results suggest that the increased serum leptin level does not have a major role in diagnosis of malnutrition in hemodialysis patients and there is a poor correlation between malnutrition parameters and serum leptin level." (PMID 20142915, 2008). "Pearson correlation coefficient for serum leptin level and adjusted leptin with malnutrition laboratory and anthropometric parameters and age, and hemodialysis duration are shown for both genders." (PMID 20142915, 2008). "Furthermore, certain infections can mimic malnutrition by downregulating leptin levels, contributing to an immune-compromised state." (PMID 40095902, 2025).
malnutrition (continued). "Moreover, malnutrition-induced downregulated leptin and increased adiponectin synthesis, along with compromised stress hormone production, limit immune cells’ pro-inflammatory responses." (PMID 40507146, 2025). "For example, it is hypothesised that malnutrition, increased levels of leptin due to repeated pancreas injury and ongoing low-grade inflammation may be factors that contribute to sarcopenia." (PMID 40299837, 2025). "Interestingly, systemic leptin levels are known to decrease in states of malnutrition and starvation, which underscores leptin’s role as a mediator between nutritional status and immune function." (PMID 40095902, 2025). "Therefore, leptin and other adipokines provide an excellent direction for future work to further enhance our understanding of the impact of malnutrition on neutrophil development and function." (PMID 39028622, 2024). "According to the presented study, leptin may be a promising biomarker of malnutrition of older patients." (PMID 36978817, 2023). "Leptin, when administered during the neonatal period, reduces consumption and mimics malnutrition." (PMID 37507901, 2023). "In addition, malnutrition leads to immunosuppression through several mechanisms, including the involvement of leptin and the hypothalamic–pituitary–adrenal axis." (PMID 37127636, 2023). "Some studies (but not others) have observed an association between low leptin levels and malnutrition in patients with severe chronic diseases (such as kidney failure and cirrhosis), independently of the level of inflammation or the fluid balance." (PMID 35011102, 2022). "We suppose it might be due to central or peripheral leptin resistance, which in this case seems to play a protective role against malnutrition and appetite decrease." (PMID 36558477, 2022). "Insulin is a signal that links metabolism with reproduction, particularly since Kiss1 neurons are sensitive to circulating metabolic signals such as leptin and insulin, which confirms their importance in mediating the body’s response to nutrition or malnutrition." (PMID 36297033, 2022). "Inflammatory infiltration, anti-sperm antigen–antibody reaction and low leptin level under malnutrition were the potential pathways of the influence of male reproduction caused by colitis, which could be further investigated." (PMID 35267960, 2022). "Additionally, hormonal disorders, including high leptin concentrations, play a role in the development of malnutrition in CKD patients." (PMID 36675692, 2022). "In this paper, we proposed that individuals with leptin deficiency-linked immunosuppression due to malnutrition are not at higher risk of developing severe COVID-19 compared to healthy, well-nourished individuals with physiologically “normal” leptin levels." (PMID 33980671, 2021). "Therefore, we set out to measure adiponectin and leptin in our two SSc cohorts and test their value in predicting future malnutrition." (PMID 33816531, 2021). "In malnutrition, leptin production decreases, while adiponectin increases." (PMID 32843118, 2021). "However, in patients undergoing HD, the serum leptin concentration was significantly and positively correlated with BMI and negatively associated with serum CRP and Malnutrition-Inflammation Score." (PMID 34673824, 2021). "Starvation and malnutrition decrease the serum leptin concentration of animals." (PMID 32842565, 2020). "Leptin is also described as an indicator of fasting or malnutrition." (PMID 32336076, 2020). "Based on the current findings regarding the role of leptin in autoimmunity it may be hypothesized that the magnitude of malnutrition among preschool children in Chicago during the 1930s was sufficient to result in some protection against autoimmune reactions." (PMID 33304252, 2020). "Besides reduced back length, a lower leptin concentration appeared to be another sign of intrauterine imprinting by malnutrition." (PMID 31842480, 2019).
malnutrition (continued). "Infectious diseases are the disease of poor who invariably suffer from malnutrition that could result from reduced serum leptin levels." (PMID 30534129, 2018). "Hence, malnutrition and low serum leptin level are playing a critical role in Leishmania infection and its pathogenesis." (PMID 30534129, 2018). "Moreover, malnutrition and serum leptin levels are directly proportional to the pathogenesis of amoebiasis, and low serum leptin plays a critical role in E. histolytica- associated diarrheal illness and extent of liver injury." (PMID 30534129, 2018). "However, it is possible that elevated leptin contributes to reduced appetite while higher adiponectin simulates inflammation, further contributing to the inflammation-malnutrition complex." (PMID 30155452, 2018). "In the present review, we will discuss the emerging role of leptin in different infectious diseases and will further highlight how malnutrition or starvation could play a role." (PMID 30534129, 2018). "VL is prevalent in poor people invariably suffering from malnutrition that could be endorsed with reduced circulating leptin levels." (PMID 29116252, 2017). "Interestingly, we observed that L. donovani infection itself reduces the serum leptin levels in malnutrition." (PMID 29116252, 2017). "The reduced GM-CSF expression with the leptin treatment in malnutrition coupled VL might be an indicator of reduced parasitized favoured monocytes proliferation, which controls parasite dissemination in the spleen." (PMID 29116252, 2017). "Since anthropometric measures of malnutrition are difficult to interpret in the setting of ascites and edema, leptin and INR may provide clinical utility as indicators of pre-clinical malnutrition and adipose tissue reserve." (PMID 27583675, 2016). "Fifth, given that low BMI (BMI <23 kg/m2) is considered a marker of malnutrition, we hypothesized that leptin levels would be an important predictor of CKD malnutrition." (PMID 27307101, 2016). "Our findings confirmed that circulating leptin levels may serve as one of the biomarkers for anemia and malnutrition, and more importantly, open new pathways for possible preventive and therapeutic intervention in CKD patients." (PMID 27307101, 2016). "Studies in mice revealed a significant influence of leptin on growth during malnutrition." (PMID 27690005, 2016). "We hypothesize that complete or relative leptin deficiency is a predictor of malnutrition in CKD, and leptin replacement may be a rational therapeutic option." (PMID 27307101, 2016). "Third, only patients with decompensated cirrhosis were studied, and the role of leptin as a biomarker of malnutrition in less advanced forms of liver disease remains unclear." (PMID 27583675, 2016). "Data from animal models have suggested that leptin may mediate the effects of malnutrition on T cell function, although little data currently exists to suggest that these effects translate into compromised specific immune responses in malnourished humans." (PMID 22609011, 2012). "While low levels of leptin may reflect a state of malnutrition in HD patients, proatherogenic effects of hyperleptinemia were linked to an adverse cardiovascular profile in general population." (PMID 21676262, 2011). "In addition, a tight connection between thymic function in malnutrition and leptin activity in this tissue has been demonstrated, reinforcing the role for leptin in the connection between metabolic and immune function." (PMID 19888448, 2009). "Malnutrition laboratory parameters and serum leptin were measured before hemodialysis." (PMID 20142915, 2008). "Several studies have shown that circulating leptin levels are modestly elevated in patients with alcoholic cirrhosis, suggesting that leptin might be involved in the malnutrition of cirrhosis." (PMID 15387890, 2004).